NEK2 (NIMA related kinase 2)
Diseases named in the same sentence as NEK2 in open-access papers (continued):
Sharing a sentence is not in itself a finding about the gene and the disease.
breast carcinoma (continued). "Breast cancers and breast cancer cell lines overexpress several mitotic regulators, including kinases that regulate the SAC such as Nek2, Mad1L1, Mad2L1, Mad2L2, BubR1, BubR1B, Bub3, Cdc20, and Mps1/TTK." (PMID 29100415, 2017). "Up-regulated genes, such as COL10A1, MMP11, NEK2, PAFAH1B3, KIF4A are highly related to breast cancer." (PMID 28245581, 2017). "We also found that Nek2 acts downstream of the Rb pathway, since Nek2 overexpression rescues back CA/CIN in Her2+ breast cancer cells silenced for Cdk4 or E2F3." (PMID 26512919, 2015). "Our group demonstrated that silencing E2F1 or E2F3 suppressed CA/CIN in Her2+ breast cancer, while their overexpression in mammary epithelial cells triggered CA/CIN that respectively correlated with decreases or increases in Nek2 protein levels." (PMID 26512919, 2015). "Studies have shown that a two-gene ratio (HOXB13:IL17BR) and a five-gene (BUB1B, CENPA, NEK2, RACGAP1, RRM2) molecular grade index (MGI) are predictive of clinical outcomes among early-stage breast cancer patients." (PMID 23497539, 2013). "While the breast cancer candidacy of CENPF, KIF14, NEK2, DTL, CKS1B, ASPM and EXO1 genes have been identified earlier, there is only one prominent report indicating the candidacy of EXO1 in breast cancers and remains to be investigated." (PMID 24147022, 2013). "Namely siRNA-mediated knockdown of Nek2 in MCF7, MDA-MB-231 and Hs578T mammary carcinoma cell lines suppressed their proliferation, invasiveness, and anchorage-independent growth in vitro." (PMID 22040655, 2011). "In addition, TUFT1 is phosphorylated by NIMA-related kinase 2 (NEK2), and the phosphorylation status of TUFT1 is essential for coordinating centrosome number and cell proliferation in cervical and breast cancers." (PMID 41022752, 2025). "Strikingly, the nontransformed cells did not respond to the NEK2 inhibitor at doses that suppressed growth of the breast cancer cell lines." (PMID 39826695, 2025). "Moreover, inhibiting NEK2 potentiates the response to CDK4/6i by amplifying their ability to induce CIN in vitro and in mouse models of breast cancer." (PMID 39826695, 2025). "Moreover, small molecule inhibitors against NEK2, such as INH1, blocked the proliferation of several breast cancer cell lines in vitro as well as reduced the growth of tumor mouse xenografts of breast cancer in vivo." (PMID 38606093, 2024). "The mRNA level analysis of NEK genes in breast cancer cell lines and breast cancer patients from various data sources revealed that NEK2, NEK4, NEK5, NEK6, NEK8, and NEK11 are overexpressed in breast cancer and may be involved in breast cancer development." (PMID 37627077, 2023). "TTK and Nek2 are significantly overexpressed in NHB women with breast cancers that do not fall within any specific molecular classification, or that failed to classify (other)." (PMID 36494865, 2022). "This study also showed that Nek2 overexpression in breast cancer cells resulted in unaligned chromosomes during metaphase, but only in the presence of TRF1, implying that TRF1 is at least one of the means by which Nek2 overexpression leads to abnormal mitosis and chromosomal instability." (PMID 35409400, 2022). "According to the existing literature, except for NEK2 the expression and prognostic significance of the NEIL3, CDC25C, and HCN2 genes are still unknown in breast cancer." (PMID 33644115, 2021). "The relapse-free survival of patients with Nek2-overexpressing tumors was significantly worse than that of patients exhibiting low expression, regardless of breast cancer subtype." (PMID 33267874, 2020). "Moreover, we observed that high grade breast cancer patients and lung adenocarcinoma patients with a high AURKA and NEK2 gene expression had a significant poor overall survival." (PMID 32033228, 2020). "Among them, NEK2, BIRC5, and TOP2A were also found to be amplified in breast cancer, suggesting that they could act as strategic players in the obese-deregulated transcriptome." (PMID 29330624, 2018).
breast carcinoma (continued). "Notably, NEK2 as well as BIRC5 and TOP2A were amplified in more than 12, 6, and 5% of breast cancers, respectively, reinforcing their potential role as key therapeutic targets." (PMID 29330624, 2018). "For instance, CENPF (Centrosome protein F) and NEK2 (NIMA (never in mitosis gene a) - related kinase 2) were reported for their association with poor prognosis and chromosomal instability in breast cancer." (PMID 24147022, 2013). "Importantly, we provide evidence that breast cancer cells are selectively dependent on NEK2, but nontransformed cells are not, in contrast with other mitotic kinases that are commonly essential in all cell types." (PMID 39826695, 2025). "Future research and clinical trials are crucial in determining the safety, efficacy, and suitability of NEK2 as a clinical therapy target or in combination with the standard of care for TNBC, offering new hope for patients facing limited treatment options in this aggressive breast cancer subtype." (PMID 38886738, 2024). "Indeed, breast cancer stem cells exhibited a marked decrease in miRNA-128 levels, and its overexpression was found to inhibit self-renewal ‘in vitro’ and tumorigenicity ‘in vivo’ by blocking the mitotic NIMA-related kinase 2 (NEK2)." (PMID 37958677, 2023). "In all breast cancer, low expression of NEIL3, CDC25C and NEK2 predicted high RFS (p < 0.05) respectively, while high expression of HCN2 predicted high RFS (p < 0.05), and low expression of NEIL3, CDC25C, NEK2 and HCN2 predicted high OS respectively (p < 0.05)." (PMID 33644115, 2021). "More important, a large number of studies showed that NEK2 overexpression occurred in many human solid tumors, including hepatocellular carcinoma (HCC), colorectal cancer (CRC), pancreatic ductal cancer, lung cancer, prostate cancer, breast carcinoma, and glioma." (PMID 30578380, 2019). "The goal of this series of experiments is to establish whether silencing E2F3 with or without the introduction of Nek2 modifies tumor progression of HCC1954 breast cancer cells in vivo." (PMID 26512919, 2015). "It is also consistent with our data showing that despite Nek2 rescuing back CA in Her2 + breast cancer cells stably silenced for E2F3, Nek2 did not influence tumor growth." (PMID 33907253, 2021). "The over-expressed CCNE1, CLGN, NEK2, PTTG1 and RAD51, and the under-expressed ADAMTS1, FOS, FOSB, IL6 and ZFP36 in tumor cells are examples of breast cancer genes without differential promoter methylation between normal and tumor samples." (PMID 25706888, 2015). "Despite the general overexpression of Nek2 and TTK shown in breast cancer, no clear information exists on whether this is a general or specific pattern related to the genetic context of patients." (PMID 36494865, 2022). "Likewise, Nek2 is another kinase we did not address, since our previous publications indicate it maintains CA and CIN in Her2+ breast cancer cells and in MCF10A cells expressing H-RasG12V or H-RasG12V and c-Myc." (PMID 25278993, 2014).
multiple myeloma (38 papers, 2014 to 2025). "Specifically, overexpression of NEK2 in the ARP-1 multiple myeloma cells causes reduced treatment efficacy of bortezomib, doxorubicin, and etoposide." (PMID 26320076, 2015). "In addition, knockout of NEK2 delays tumor progression by significantly reducing the infiltration of tumor-associated macrophages and T cell depletion in multiple myeloma." (PMID 40220284, 2025). "This hypothesis was in line with evidence that up-regulation of NEK2 in myeloma prognosticates inferior survival and is strongly associated with CIN and drug resistance." (PMID 25230277, 2014). "The apparent association of high ALDH1A1 and NEK2 levels is consistent with the hypothesis that NEK2 contributes to ALDH1A1-dependent drug resistance in myeloma." (PMID 25230277, 2014). "In multiple myeloma, NEK2 inhibits its own and Beclin1 degradation by binding to ubiquitin-specific protease 7(USP7), thereby activating classical NF-κB signaling and autophagy pathways, promoting disease progression and resistance to bortezomib." (PMID 38503948, 2025). "Many studies have shown that NEK2 is found in many human cancers, including non-small cell lung cancer, myeloma, ovarian cancer, BC, prostate cancer, colorectal cancer, malignant peripheral nerve sheath tumor, and pancreatic ductal adenocarcinoma." (PMID 35368696, 2022). "NEK2 has shown it is involved in some different cancers: NEK2 promotes aerobic glycolysis in multiple myeloma; targeting NEK2 attenuates glioblastoma growth and radioresistance; NEK2 can be a prognostic biomarker of hepatocellular carcinoma." (PMID 33726794, 2021). "For example, J Xia demonstrated that NEK2 induces autophagy-mediated bortezomib resistance by stabilizing Beclin-1 in multiple myeloma." (PMID 33971811, 2021). "Our previous studies indicated that high NEK2 confers inferior survival in multiple myeloma (MM); thus, a better understanding of the mechanisms by which NEK2 induces drug resistance in MM is required." (PMID 31955515, 2020). "Datas indicated that the USP7 inhibitor P5091 was overcoming bortezomib resistance in multiple myelomas by destabilizing NEK2." (PMID 32002017, 2020). "USP7 inhibitors show great efficacy for inhibiting myeloma cell growth and overcoming NEK2-induced and acquired drug resistance in xenograft myeloma mouse models." (PMID 31730000, 2019). "Nek2 plays a role in spindle formation and chromosome segregation and its expression is increased in myeloma resulting in aneuploidy and CIN." (PMID 29163849, 2017). "Our data demonstrate that knockdown of NEK2 in myeloma cells decreased expression of PKM2 and the ratio of PKM2/PKM1." (PMID 28086949, 2017). "Together, NEK2 promotes aerobic glycolysis through activating pyruvate kinase mRNA splicing in myeloma cells." (PMID 28086949, 2017). "The clinical data for survival analyses indicate that myeloma patients with high NEK2 and PKM2 had the shortened survival." (PMID 28086949, 2017). "NEK2 represents a strong predictor for drug resistance and poor prognosis in cancer, in that targeting NEK2 by NEK2 shRNA overcame drug resistance and induced apoptosis in vitro and in a myeloma PDX model." (PMID 28499452, 2017). "Similar to hnRNPA1/2, the expression of NEK2 was regulated by c-Myc at transcription level in myeloma cells." (PMID 28086949, 2017). "In summary, our studies show the first evidence that NEK2 plays a functional role in aerobic glycolysis and provide mechanistic insights how NEK2 promotes aerobic glycolysis in myeloma." (PMID 28086949, 2017).
multiple myeloma (continued). "Myeloma patients with high expression of NEK2 and PKM2 have lower event-free survival and overall survival." (PMID 28086949, 2017). "We believe that inhibitors of the following targets hold a great deal of promise for myeloma therapy: aurora kinase A, NEK2, PLKs and Mps1 kinase." (PMID 29100463, 2017). "Consistently, the expression of HK2, ENO1, LDHA, glucose transporter type 4 (Glut4), and monocarboxylate transporter 4 (MCT4) was downregulated in NEK2 silenced myeloma cells." (PMID 28086949, 2017). "NEK2 regulates the alternative splicing of PKM immature RNA in multiple myeloma cells by interacting with hnRNPA1/2." (PMID 28086949, 2017). "In contrast, knocking down NEK2 by shRNA reversed these phenotypes in vitro and in a xenograft myeloma mouse model in vivo." (PMID 29100463, 2017). "We recently performed a tandem affinity purification followed up by mass spectrometry (TAP-MS) analysis and identified that NEK2 binds to hnRNPA proteins in myeloma cells." (PMID 28086949, 2017). "Downregulation of NEK2 by shRNA inhibited myeloma cell growth and decreased drug resistance in vitro and in NOD-Rag/null gamma mice." (PMID 26320076, 2015). "The serine/threonine kinase Nek2 is commonly found upregulated in a wide variety of neoplasms including diffuse large B cell lymphoma and multiple myeloma." (PMID 25485281, 2014). "We also demonstrate that over-expression of ALDH1A1 in myeloma leads to elevated NEK2 levels, using a mechanism that includes 9-cis retinoic acid-dependent RXRα signaling." (PMID 25230277, 2014). "Nek2 expression is an important mediator in multiple myeloma, an end stage of B cell neoplasm, so we queried the importance of Nek2 in B cell development." (PMID 25485281, 2014). "Recent studies have shown that high Nek2 expression is correlated with drug resistance in multiple myeloma patients." (PMID 25313354, 2014). "Treatment with these novel Nek2 inhibitors successfully mitigated drug resistance in bortezomib-resistant multiple myeloma." (PMID 25313354, 2014). "To investigate the role of Nek2 in bortezomib resistance, we ectopically overexpressed Nek2 in several cancer cell lines, including multiple myeloma lines." (PMID 25313354, 2014). "A study by our group has shown that high Nek2 expression is correlated with poor prognosis in myeloma patients due to increased activity of drug efflux pumps as the result of Nek2 activating the AKT pathway." (PMID 25485281, 2014). "Taken together, our results introduce Nek2 as a therapeutic target in bortezomib-resistant multiple myeloma." (PMID 25313354, 2014). "We previously defined a mechanism for the induction of drug resistance by Nek2 and demonstrated that overexpression of Nek2 activates Akt which results in drug resistance and cellular proliferation in multiple myeloma." (PMID 25485281, 2014). "The activation of NEK2 in myeloma cells relied on the ALDH1A1-dependent generation of the retinoid X receptor α (RXRα) ligand, 9-cis retinoic acid (9CRA) – not the retinoic acid receptor α (RARα) ligand, all-trans retinoic acid (ATRA)." (PMID 25230277, 2014). "Our previous study demonstrated that as many as 5 of 17 genes found to be significantly up-regulated in ALDH1+ myeloma cells encode cell cycle-dependent protein kinases; specifically, CDC2, TTK, AURKA, AURKB and, of importance here, NEK2." (PMID 25230277, 2014). "Among the genes studied, we found that Nek2 most accurately predicted poor prognosis, cell proliferation, and drug resistance in ex vivo and in vitro models of multiple myeloma." (PMID 25313354, 2014). "Moreover, USP7 plays a crucial role in multiple myeloma resistance development by binding the NIMA-related kinase 2 (NEK2)." (PMID 41157055, 2025). "Finally, abnormal expression of NEK2 has been observed in various cancers, including lung, pancreatic, prostate, and breast, as well as hepatocellular carcinoma and multiple myeloma." (PMID 40564876, 2025).
multiple myeloma (continued). "While NEK2 inhibitors have been widely established, and the efficacy was tested in both in vitro and in vivo in several types of cancer, including multiple myeloma, leukemia, gastric, colorectal, glioma, breast, and liver cancers, their effect on lung cancer requires further investigation." (PMID 36499051, 2022). "Thus, silencing PKM2, a pyruvate kinase muscle isozyme that is positively regulated by the Myc-NEK2 axis in myeloma cells, inhibits myeloma." (PMID 35794249, 2022). "In Wen's study, overexpression of NEK2 in cancer cells resulted in enhanced chromosomal instability, cellular proliferation, and drug resistance; while NEK2 knockdown overcame cancer cell resistance to drugs and induced apoptosis in vitro and in a xenograft myeloma mouse model." (PMID 33754007, 2021). "FOXM1’s interaction in myeloma cells with NEK2 (NIMA-related kinase 2) and the CDK4/6-Rb-E2F axis is of interest from a therapeutic viewpoint because CDK inhibition may be effective in myeloma." (PMID 30463534, 2018). "We also speculate that targeting aerobic glycolysis may overcome NEK2 induced drug resistance in multiple myeloma." (PMID 28086949, 2017). "The expression of NEK2 and glycolysis-enhancing genes, such as hexokinase 2 (HK2), alpha-enolase (ENO1), and lactate dehydrogenase A (LDHA), was significantly increased in high-risk myeloma samples and positively correlated each other." (PMID 28086949, 2017). "Aldehyde dehydrogenase 1 (ALDH1) is also involved in NEK2-dependent CIN in myeloma." (PMID 29100463, 2017). "Western blotting results confirmed that NEK2 was overexpressed in myeloma cells." (PMID 28086949, 2017). "Moreover, a correlation between Nek2 expression and drug resistance, relapse and poor outcome is also reported in myeloma." (PMID 29163849, 2017). "Previous studies have demonstrated that NEK2 promotes drug resistance in multiple myeloma, it is very likely that enhanced aerobic glycolysis by NEK2 may contribute to its function in drug resistance." (PMID 28086949, 2017). "We further examined whether NEK2 regulates alternative splicing of PKM pre-mRNA in NEK2 silencing myeloma cells." (PMID 28086949, 2017). "The ratio of PKM2/PKM1 was significantly decreased in myeloma NEK2-silenced cells." (PMID 28086949, 2017). "Over expression in myeloma cells may lead to increased mRNA and protein levels of NEK2, to elevated clonogenicity of myeloma and tumor formation in mice, and to resistance to myeloma drugs in vitro and in vivo." (PMID 29100463, 2017). "Our data indicate that NEK2 is transcriptionally regulated by c-Myc in myeloma cells." (PMID 28086949, 2017). "In this study, we determine whether NEK2 increases PKM splicing and PKM2 expression resulting in high aerobic glycolysis in myeloma cells using engineered isogenic myeloma cell lines with over or lower expression of NEK2." (PMID 28086949, 2017). "Our understanding of Nek2's importance in regulation of the cell cycle, disease progression, and drug resistance has improved dramatically leading to the development of Nek2 as a poor prognostic marker in myeloma and other cancers." (PMID 25485281, 2014). "The interaction between HEC1 and Nek2 provides an attractive therapeutic target within myeloma." (PMID 25485281, 2014). "As we previously reported, Nek2 also has a role in the progression of multiple myeloma." (PMID 25485281, 2014). "Because cell cycle-dependent protein kinases are thought to be a major underlying reason for CIN and drug resistance in cancer, we hypothesized that NEK2 might be involved in the mechanism by which ALDH1A1 promotes therapy resistance in myeloma." (PMID 25230277, 2014). "To elucidate the mechanism by which ALDH1A1 activates NEK2 in myeloma, we interrogated the chromatin immunoprecipitation sequencing (ChIP-Seq) database from the University of California Santa Cruz (UCSC) for chromatin occupancy patterns at the NEK2 promoter and NEK2 coding region." (PMID 25230277, 2014).